ANO1 (anoctamin 1)
Diseases named in the same sentence as ANO1 in open-access papers (continued):
Sharing a sentence is not in itself a finding about the gene and the disease.
breast cancer (continued). "In prostate cancer, breast cancer, and PDAC, Ani9 inhibits ANO1 synthesis in a concentration-dependent manner, reducing the proliferation and invasive capabilities of cancer cells." (PMID 40396170, 2025). "Study has shown that suppression of ANO1 expression significantly inhibits the phosphorylation of CAMKII, EGFR, Akt, and ERK1/2 in breast cancer, HNSCC, and ESCC cells." (PMID 40356890, 2025). "Calcium-activated chloride channels, such as that formed by the Anoctamin 1 (ANO1) protein, frequently amplified and played an important role in various cancers, such as breast cancer, ovarian cancer, and bladder cancer." (PMID 36142409, 2022). "It is reported that ANO1 interacts with EGFR and affects EGFR-targeted therapy in HNSCC and breast cancer." (PMID 33901011, 2021). "ANO1 is also upregulated in multiple tumor tissues, including head and neck squamous cell carcinoma (HNSCC), and prostate and breast cancer." (PMID 33901011, 2021). "STAT3 is important for ANO1 transcription in response to IL-6 in pancreatic acinar cells and in response to EGF in breast cancer cells." (PMID 33250781, 2020). "The possibility that ANO1 might be involved in the tumorigenesis has been suggested by its chromosomal location at 11q13 because this loci is frequently amplified in various human malignant tumors, such as head and neck cancer, breast carcinoma (BCA), lung cancer, and esophageal cancer." (PMID 29416639, 2018). "Consistent with the proliferation-promoting effect of Ano1 in MCF7 cells, several in vitro studies have shown the proliferation-promoting effect of Ano1 in HNSCC, breast cancer, and prostate cancer." (PMID 29156699, 2017). "Ano1 overexpression promotes cell proliferation in tumors such as HNSCC, breast cancer, glioma, and prostate cancer, as well as interstitial cells of Cajal and renal cyst-forming epithelial cells." (PMID 29156699, 2017). "The upregulation of ANO1 has also recently been reported in colon cancer and lung adenocarcinoma, and is correlated with poor prognosis of HNSCC and breast cancer." (PMID 27732935, 2016). "It has been shown that ANO1 promotes cell proliferation and tumor growth in HNSCC and breast cancer by activating MAPK signaling pathway and activating EGFR and CAMK signaling respectively." (PMID 27732935, 2016). "ANO1 inhibition subsequently leads to the reduction in phosphorylation of ERK1/2, AKT and v-src in breast cancer cells, HNSCCs, and esophageal squamous carcinoma cell lines." (PMID 26811235, 2016). "ANO1 overexpression is also correlated with poor prognosis of HNSCC and breast cancer patients, and pharmacological inhibition of CaCC ANO1 activity by CaCCinh-A01 and T16Ainh-A01 can inhibit cancer cell proliferation." (PMID 26305547, 2015). "In HER2-postive breast cancer, it is possible that excessive activation of HER2 predominately controls the signaling pathway, thus masking the activation of EGFR signaling by Ano1." (PMID 25961581, 2015). "Ano1 has been found to activate the EGFR signaling pathway, and promotes breast cancer tumorigenesis." (PMID 25961581, 2015). "In the present study, we identified that the expression of Ano1 was higher in PR-positive tumors compared with PR-negative tumors, especially in the ER-negative patients, suggesting that the ER and PR signaling pathways may be involved in Ano1 overexpression in breast cancer." (PMID 25961581, 2015). "Multivariate Cox regression analysis was performed to evaluate the impact of Ano1 expression on the RFS and OS in breast cancer patients." (PMID 25961581, 2015). "ANO1 has been identified as an important survival factor in human cancers and contributes to HNSCC, ESCC, and breast cancer tumorigenesis, making it a promising therapeutic target (2, –, 7)." (PMID 24599954, 2014). "In mammary cancer, where TMEM16A (ANO-1) is also over-expressed and supports proliferation, it is linked to EGF receptor and calmodulin-dependent kinase II signaling." (PMID 24009588, 2013).
breast cancer (continued). "ANO1 has also been shown to mediate EGFR signalling in HNSCC and breast cancer cells." (PMID 36497413, 2022). "In particular, a member of the Ca2+–activated chloride channels, TMEM16A, also known as ANO1, was proposed to contribute to tumor growth and invasion in head and neck squamous cell carcinomas, breast cancer, hepatocellular carcinoma, lung cancer, gastric cancer, and prostate cancer." (PMID 33562306, 2021). "In addition to normal tissues, ANO1 is highly expressed in various types of cancers, including head and neck squamous cell carcinoma (HNSCC), breast cancer, pancreatic cancer, prostate cancer, thyroid cancer, and glioblastoma." (PMID 32357567, 2020). "Knockdown or pharmacological inhibition of ANO1 in ZR75-1 and HCC1954 breast cancer cell lines resulted in a decreased phosphorylation of EGFR at Y992 as well as of phosphorylation of downstream signaling molecules - ERK1/2, AKT and calmodulin kinase II (CaMKII) under normal growth conditions." (PMID 33250781, 2020). "In a recent study, Huizhe Wu reveals that the calcium-activated chloride channel Ano1 promotes cell proliferation in ER-positive, PR-positive, and HER2-negative breast cancer cell, but inhibits cell growth in ER-negative, PR-negative, and HER2-negative breast cancer cells." (PMID 30813939, 2019). "Gene profiling of tumors by meta-analyses from microarray data sets shows that ANO1 and FADD, both located on chromosome 11q13, can serve as prognostic markers for breast cancer and head and neck cancer, indicating a critical role of ANO1 in FADD-mediated apoptosis." (PMID 29899325, 2018). "We then investigated the association of the expression of Ano1 and Ki67 with the OS or DFS in breast cancer patients with lymph node-positive or node-negative status." (PMID 29156699, 2017). "Our study suggests that Ano1 expression in combination of clinical relevant markers ER, PR, HER2, and Ki67 is useful for predicting clinical outcomes of breast cancer patients, especially those with luminal A breast cancer, following tamoxifen treatment." (PMID 29156699, 2017). "In this study, we found a negative correlation between Ano1 and Ki67 in breast cancer samples, and the negative correlation was supported by Ano1 overexpression inhibited cell proliferation in MDA-MB-435S cells." (PMID 29156699, 2017). "Previous investigations from others and ours have shown that ANO1 is amplified or overexpressed in various cancers including head and neck squamous cell carcinoma (HNSCC), prostate cancer, breast cancer, colon cancer and lung adenocarcinoma, making it a promising tumor marker." (PMID 27732935, 2016). "In the present study, we found that Ano1 expression levels were not correlated with tumor size, histological grade, and lymph node metastasis in all breast cancer patients as well as those with different ER, PR, and HER2 status." (PMID 25961581, 2015). "A few over-expressed genes in cancer are also located in the amplified region of 11q13.3, including MYEOV (myeloma over expressed), ORAOV1 (oral cancer over expressed gene 1), ANO1 in head and neck squamous cell carcinoma, and CTTN in breast cancer and squamous cell carcinomas of the head and neck." (PMID 26386145, 2015). "Amplification of ANO1 correlates with poor overall survival in HNSCC and breast cancer." (PMID 24599954, 2014). "ANO1 is amplified and highly expressed in HNSCC, ESCC, and breast cancer." (PMID 24599954, 2014). "Knockdown of ANO1 in MCF-7 or T47D breast cancer cells resulted in a reduced tyrosine phosphorylation of EGFR (the site is not reported) and of STAT3 transcription factor in response to EGF, whereas overexpression of ANO1 in T47D cells increased phosphorylation EGFR and STAT3." (PMID 33250781, 2020). "In addition, overexpression of various Ano1 isoforms identified in breast cancer cells does not affect cell proliferation in HEK-293 cells." (PMID 29156699, 2017).
breast cancer (continued). "However, although we found that Ano1 overexpression promoted cell proliferation in MCF7 cells, no positive correlation between Ano1 overexpression and Ki67 was found in human breast cancer samples." (PMID 29156699, 2017). "In addition, pharmacological inhibition of CaCC activity of ANO1 reduced cell viability in HNSCC, esophageal squamous cell carcinoma (ESCC) and breast cancer cells via inhibition of epidermal growth factor receptor (EGFR) and calmodulin-dependent protein kinase II (CAMKII) signaling." (PMID 26196390, 2015). "The high expression of Ano1 was significantly associated with longer OS in patients with PR-positive (p = 0.026), or HER2-negative (p = 0.010), but not HER2-postive (p = 0.478), breast cancer." (PMID 25961581, 2015). "However, the proliferation-promoting effect of Ano1 is not observed in HEK-293 cells overexpressing various Ano1 isoforms that are identified in breast cancer cells." (PMID 25961581, 2015). "Human breast cancer tissues contain heterogeneous cell populations, and it may be possible that a signaling pathway that promotes cell proliferation and inhibits Ano1 expression may be activated in breast cancer tissues, but not in cultured cells in our experimental conditions." (PMID 29156699, 2017). "Although Ano1 expression was not significantly different between HER2-positive and HER2-negative breast cancer, Ano1 expression was significantly higher in breast cancer with HER2 IHC staining of 3+ compared with breast cancer with HER2 IHC staining of 0–1+." (PMID 25961581, 2015). "A number of other cell lines from different tumor types also had high-level ANO1 amplifications (data not shown), consistent with frequent amplifications of ANO1 in head and neck squamous carcinoma (HNSCC), bladder, and breast cancers as part of the amplification of the chromosomal region 11q13." (PMID 36461044, 2022).
head and neck squamous cell carcinoma (61 papers, 2012 to 2025). A squamous cell carcinoma that arises from any of the following anatomic sites: lip and oral cavity, nasal cavity, paranasal sinuses, pharynx, larynx, and salivary glands. "In line with our results, higher expression of ANO1 was associated with shorter OS of gastric carcinoma, head and neck squamous cell carcinoma, and esophageal squamous cell carcinoma patients." (PMID 29416639, 2018). "In head and neck squamous cell carcinomas, inhibition of ANO1 increased migration activity, which was associated with decreased expression of E-cadherin." (PMID 29416639, 2018). "Pharmacological inhibition of ANO1 has demonstrated anticancer effects in head and neck squamous cell carcinoma (HNSCC), esophageal squamous cell carcinoma (ESCC), gastrointestinal stromal tumors, CRC, and NSCLC." (PMID 40520165, 2025). "In head and neck squamous cell carcinoma (HNSCC), ANO1 amplification is associated with poor patient survival, and PDX models have demonstrated that ANO1 inhibition reduces cell migration and invasion." (PMID 40707942, 2025). "In agreement with this idea, several previous studies have reported that ANO1 expression is regulated by epigenetic mechanisms involving promoter DNA methylation in head and neck squamous cell carcinomas and salivary glands." (PMID 38773164, 2024). "Anoctamin1 (ANO1), a calcium-activated chloride channel, is involved in the proliferation, migration, and invasion of various cancer cells including head and neck squamous cell carcinoma, lung cancer, and prostate cancer." (PMID 36674697, 2023). "In particular, there is a very strong correlation between the amplification and expression of ANO1, and the overall survival rate of head and neck squamous cell carcinoma patients with high ANO1 protein expression is poor." (PMID 34769467, 2021). "Our aim was to elucidate the molecular mechanisms of how ANO1 contributes to oncogenic processes in squamous cell carcinoma of the head and neck (HNSCC)." (PMID 33803266, 2021). "ANO1 is a calcium-activated chloride channel that is frequently overexpressed in head and neck squamous cell carcinoma (HNSCC) and other cancers." (PMID 29123240, 2017). "In head and neck squamous cell carcinoma, Ano1 activates the ERK1/2 and increases the levels of cyclin D1." (PMID 25961581, 2015). "ANO1 is mapped to the chromosomal band 11q13 that is frequently amplified in a variety of human carcinomas including head-and-neck squamous cell carcinoma (HNSCC), GIST, breast and prostate cancer." (PMID 26196390, 2015). "The Ca2+-activated Cl− channel TMEM16A (ANO-1) is overexpressed in many carcinomas, including human prostate carcinoma and head and neck squamous cell carcinomas, where it induces stimulation of ERK1/2 and contributes to cell proliferation." (PMID 24009588, 2013). "ANO1 is located on chromosome 11q13, which is frequently amplified in malignant tumors, and is reported to be highly expressed in glioblastoma, head and neck squamous cell carcinoma, gastrointestinal cancer, pancreatic cancer, esophageal cancer, breast cancer, and prostate cancer." (PMID 38892219, 2024). "Moreover, the expression of ANO1 was significantly correlated with shorter survival of gastric carcinomas and head and neck squamous cell carcinomas." (PMID 29416639, 2018). "The coding sequence of Ano1 is located within the 11q13 region, a chromosomal locus that is frequently amplified in a number of different human cancers, such as urinary bladder cancer, breast cancer and head and neck squamous cell carcinoma (HNSCC)." (PMID 22912841, 2012). "Moreover, ANO1 has been investigated in additional cancers, including head and neck squamous cell carcinoma (HNSCC), where its amplification and elevated expression were associated with poor survival outcomes, indicating its potential as a prognostic marker and therapeutic target." (PMID 40707942, 2025).
head and neck squamous cell carcinoma (continued). "Studies performed in head and neck squamous cell carcinoma (HNSCC) indicate that a high expression of ANO1 is related to metastatic processes in lymph nodes, poor prognosis, and the poor survival of patients with OSCC and ESCC." (PMID 37408210, 2023). "This study investigates the clinical significance of Anoctamin-1 gene mapping at 11q13 amplicon in both the development and progression of head and neck squamous cell carcinomas (HNSCC)." (PMID 26498851, 2015). "ANO1 was shown to be upregulated in several cancer tissues including head and neck squamous cell carcinoma (HNSCC) and prostate-, breast-, and pancreatic cancer." (PMID 25163766, 2015). "ANO1 also activates the Ras-Raf-MEK-ERK1/2 signaling pathway, contributing to the development of head and neck squamous cell carcinoma and colon cancer." (PMID 38352864, 2024). "Recent evidence suggests that ANO1 is a potential therapeutic target for various cancers, including gastrointestinal stromal cancer (GIST), head and neck squamous cell carcinoma (HNSCC), and oral squamous cell carcinoma (OSCC)." (PMID 38892219, 2024). "In head and neck squamous cell carcinoma (HNSCC), EGFR was found to be in a mutually interactive protein–protein complex with CaCC (ANO1/TMEM16A)." (PMID 35681682, 2022). "ANO1 is involved in epithelial tumor formation and is highly amplified and expressed in OSCC, head and neck squamous cell carcinoma, prostate cancer, breast cancer and esophageal cancer." (PMID 34769467, 2021). "It was reported that ANO1 forms a direct complex with EGFR through the trans/juxtamembrane domain of EGFR in head and neck squamous cell carcinoma (HNSCC) cells; knockdown of ANO1 resulted in greatly reduced EGFR protein levels, which functionally translated to decreased cell proliferation." (PMID 33250781, 2020). "In some cancer types, such as glioma, head and neck squamous cell carcinoma (HNSCC), colorectal cancer, and prostate carcinoma, inhibition of ANO1 promoted not only reduction of tumor size and cell proliferation, but also decrease in migration, invasion, and metastasis." (PMID 34281197, 2021). "The shRNA- or siRNA-mediated inhibition of ANO1 suppressed proliferation and invasiveness of human BCA cells, lung cancer cells, colorectal cancers, prostatic cancers, hepatocellular carcinomas, and head and neck squamous cell carcinomas." (PMID 29416639, 2018). "In addition, the prognostic significance of immunohistochemical expression of ANO1 differed between HPV-positive and HPV-negative head and neck squamous cell carcinomas." (PMID 29416639, 2018). "A previous study reported that ANO1 expression is regulated by epigenetic mechanisms involving DNA methylation of the ANO1 gene promoter region in head and neck squamous cell carcinomas, but similar studies have not been conducted on normal salivary gland tissue." (PMID 31847128, 2019).